TP53INP1 (tumor protein p53 inducible nuclear protein 1)
Diseases named in the same sentence as TP53INP1 in open-access papers (continued):
Sharing a sentence is not in itself a finding about the gene and the disease.
tumor (continued). "Perhaps, TP53INP1 can act either as a tumor suppressor gene or an oncogene depending on the tissue type or the tumor microenvironment." (PMID 23717325, 2013). "The primary orthotopic tumour weight was increased by 2.2, 2.1 and 6.2-fold in TP53INP1, LATS2 and CD44 silenced MIA PaCa-2 cells, respectively." (PMID 23857777, 2013). "In this scenario, overexpression of TP53INP1 actually results in increased tumorigenesis, contradicting with the tumor suppressor characteristic of TP53INP1 as described in various other cancers, suggesting a tissue specific function." (PMID 23717325, 2013). "As a tumor suppressor, TP53INP1 has been reported to be down-regulated in cancers from different organs." (PMID 23717325, 2013). "Upregulation of anti-apoptotic genes, including BAG1, BCL11B and SERPINB2, and downregulation of apoptotic genes, such as DAPK2, HRK and TP53INP1, can promote tumor cell survival." (PMID 23024765, 2012). "TP53INP1 is involved in stress response and apoptosis, and its interaction with miR-155 may contribute to cell survival under tumor-promoting conditions." (PMID 41345725, 2025). "Restoring TP53INP1 expression could inhibit tumor growth through its anti-proliferative, pro-apoptotic, pro-autophagic, and anti-cell migration activities." (PMID 39108882, 2024). "TP53INP1 acts as a classic tumor suppressor that is regulated by upstream proteins." (PMID 38436783, 2024). "The involvement of TP53INP1 in GBM tumor growth and therapy resistance needs further study." (PMID 38259614, 2023). "However, in human BC, MicroRNA-155-5p promotes tumor development and contributes to paclitaxel resistance via TP53INP1." (PMID 36755123, 2023). "Increasing the levels of TP53INP1 could be crucial in controlling tumor growth through autophagy-dependent cell death." (PMID 37628602, 2023). "Recent studies have found that TP53INP1 is also closely related to tumor drug resistance." (PMID 37993867, 2023). "Moreover, Z-VAD-FMK, a caspase inhibitor, attenuated the inhibitory role of miR-106a in cell death induced by TP53INP1 overexpression, indicating that the inhibition of caspase-dependent apoptosis is critical for miR-106 to maintain tumour cell survival." (PMID 34718338, 2021). "Consistently, we found that several pro-apoptotic proteins, such as p21, Bax and Pig3, were shown to be regulated by miR-106a/TP53INP1, suggesting that miR-106a/TP53INP1-modulated autophagy could be a mechanism for tumour suppression." (PMID 34718338, 2021). "It was widely recognized that TP53INP1 gene is an important tumor suppressor." (PMID 33046975, 2020).
tumor (continued). "In addition, TP53INP1, which acts as a tumor suppressor by inducing cell death via caspase-dependent autophagy, was identified as a target of miR-221 through luciferase reporter assay." (PMID 32477928, 2020). "To confirm their interactions, we first treated tumor cells with actinomycin D to assess the rate of TP53INP1 mRNA decay and found that the half-life of TP53INP1 mRNA was significantly extended in MSI2a-overexpressing TNBC cells but significantly shortened in MSI2a-knockdown TNBC cells." (PMID 32448269, 2020). "Finally, immunohistochemistry results indicated that the expression levels of Snail, VE‐cadherin, MMP2 and HIF‐1α were reduced in tumours with TP53INP1 overexpression, and the expression of E‐cadherin was increased." (PMID 29655255, 2018). "We found that over-expression of TP53INP1 could significantly abrogate the tumor promoting effect of miR-125b." (PMID 26388699, 2015). "The expression of TP53INP1 was significantly lower in tumor tissues compared with adjacent tissues." (PMID 26388699, 2015). "Tumor protein 53-induced nuclear protein 1 gene expression is often silenced in tumor cells due to oncogenic factors such as the micro RNAs miR-93, miR-130b, miR-155, miR-125b, miR-17-5p, and miR-17, which down-regulate TP53INP1 expression through post-transcriptional mechanisms." (PMID 23717325, 2013). "We propose that restoring TP53INP1 gene expression through targeting its silencers, such as miR-125, could effectively inhibit tumor invasion and metastasis." (PMID 23717325, 2013). "TP53INP1 can work as a tumor suppressor by repressing tumor cell migration during metastasis." (PMID 23717325, 2013). "The majority of the tumours from the TP53INP1, LATS2 and CD44 silencing group were poorly differentiated, and the tumour area percentage were more than 80%, while most of the tumours from the MIA-V control group were well differentiated, and the tumour area percentage were less than 20%." (PMID 23857777, 2013). "Furthermore, tumours from the TP53INP1, LATS2 and CD44 silencing group showed increased cell proliferation as indicated by the strong staining of Ki67, compared with that of the MIA-V group." (PMID 23857777, 2013). "Additionally, we will discuss the diverse functions of TP53INP1 in cancer such as induction of autophagy and repression of tumor cell migration, and highlight its potential as a therapeutic target in cancer treatment." (PMID 23717325, 2013). "As TP53INP1 expression is frequently silenced or completely lost in human cancer tissues, restoration of TP53INP1 expression could potentially inhibit tumor growth via its anti-proliferative, pro-apoptotic, pro-autophagic, and anti-cell migration activities." (PMID 23717325, 2013). "These suggest that TP53INP1 play an important role in suppression of tumor progression." (PMID 21970405, 2011).
tumor (continued). "Furthermore reduced TP53INP1 correlates with tumor progression and poor outcomes, thereby suggesting that TP53INP1 mRNA or protein levels might be an indicator of disease outcome in cancer patients." (PMID 26425652, 2015). "Beyond CDKN1A and TP53INP1, ACER2 also plays a critical role in the DNA damage response and multiple lines of evidence support its role as a tumor suppressor in cancer cells." (PMID 41345520, 2025). "We also investigated TP53INP1 and P21’s phenotypic effects in ESCC, finding that their knockdown significantly increases tumor proliferation, highlighting their crucial role in ESCC tumorigenesis." (PMID 38436783, 2024). "Twenty genes that were commonly upregulated by NTX-301 in the three different CCLs were involved in immune activation, and these genes included known tumor suppressors such as BTG2, ALOX5, SOCS1, and TP53INP1." (PMID 36980623, 2023). "Tumour suppressor genes expression levels (APOL1, TP53INP1 and ZC3H12A) were low in BLCA tissues comparing with normal bladder." (PMID 33960661, 2021). "Deregulation of the validated miR-17~92 targets, including E2F1, TP53INP1, TGFβ and PTEN, is known to contribute to uncontrolled cell proliferation, tumor growth, apoptosis and metastasis 39,49." (PMID 32174776, 2020). "In summary, the results of this study identified the TCONS_00026334 acts as an anti‐tumor and anti‐metastatic gene to inhibit CRC development by competitively binding miR‐548n, upregulating TP53INP1 expression." (PMID 32986920, 2020). "Tumours in the TP53INP1‐silenced group expressed more Snail, VE‐cadherin, MMP2 and HIF‐1α protein than the control group tumours." (PMID 29655255, 2018). "Among 148 candidates, 4 are potential tumor suppressors including Bmf, adenomatous polyposis coli (APC), START domain containing 13 (STARD13), and TP53INP1." (PMID 21970405, 2011). "In addition, in vivo tumor formation assay confirmed that forced miR-125b expression promoted proliferation potential of ishikawa cells, and tumor suppressor gene Tumor Protein 53-Induced Nuclear Protein 1 (TP53INP1) was identified to be the direct target of miR-125b." (PMID 21970405, 2011). "In total, we think that the decreased expression of MTHFR expression caused by the miR-22-3p and miR-149-5p mimic might inhibit the promoter methylation of TP53INP1 and PDCD4, thereby increasing TP53INP1 and PDCD4 expression and tumor suppression." (PMID 35723348, 2022). "After restoring the TP53INP1 expression, the tumour grew slowly, and none of the TP53INP1-treated mice developed BM." (PMID 34718338, 2021). "Furthermore, we examined the effect of miR-106a/TP53INP1 axis on cell death and EMT contributing to tumour cell metastasis." (PMID 34718338, 2021).
tumor (continued). "In addition to LATS2, many other tumor suppressors such as PPP6C, DKK1, TNFAIP1 and TP53INP1 are also verified as direct targets of miR-373, implying that miR-373 promotes cell proliferation and tumor growth under certain conditions." (PMID 25990556, 2015). "However, like TP53INP1, TP53INP2 is involved in the control of tumor development by modulating autophagy." (PMID 23717325, 2013). "Meanwhile, we observed that TP53INP1‐negative tumour cells had relationship with VM formation." (PMID 29655255, 2018).
cancer (59 papers, 2010 to 2026). A tumor composed of atypical neoplastic, often pleomorphic cells that invade other tissues. "Two of the PADI4 variants and the TP53INP1 variant have been detected in other cancer types in the COSMIC database." (PMID 38259614, 2023). "Recent studies demonstrated that TP53INP1 was associated with chemoresistance of breast cancer by potentiating drug‐induced apoptosis in cancer cells." (PMID 35587712, 2022). "TP53INP1-deficient mice, which lack participation of TP53INP1 in stress resolution, are prone to stress-induced dysfunctions including cancer." (PMID 25828351, 2015). "Deficiency in TP53INP1 expression results in increased tumorigenesis, whereas TP53INP1 expression is repressed during early stages of cancer by factors such as miR-155." (PMID 23717325, 2013). "Similarly, exosomal miR‐106b derived from cancer‐associated fibroblasts served a crucial role in GEM resistance by targeting TP53INP1 in PC." (PMID 35587712, 2022). "However findings in recent years have shown a significant reduction or loss of TP53INP1 expression during the development of cancers of the breast, stomach, and pancreas." (PMID 21970405, 2011). "Studies have demonstrated a significant reduction or loss of TP53INP1 expression in the ESCC, and low expression levels of TP53INP1 have been linked to a poor prognosis in various cancers." (PMID 38436783, 2024). "In another form of cancer (hepatocellular carcinoma), TP53INP1 downregulation has been shown to promote cancer metastasis through the DUSP10/ERK signaling pathway." (PMID 38201290, 2023). "Other studies have also found that miRNAs can affect the proliferation and migration of cancer cells by regulating the expression of TP53INP1 and PDCD4." (PMID 35723348, 2022). "Among the enriched CCs, The cytoplasm (associated with 6 KGs: OAS1, OAS3, IRF9, HPGD, TP53INP1 and NQO1) has been found to be associated with most proteins that are highly expressed for cancer." (PMID 35617355, 2022). "This study showed that the TP53INP1 expression in OSCC is consistent with former research that it is often lost during cancer development from different organs." (PMID 35070952, 2021). "We now show that TP53INP1 is a target of miR-221, and the overexpression of miR-221 can promote cancer cell migration and invasion through the TP53INP1/p-ERK1/2 axis." (PMID 32477928, 2020). "The expression of TP53INP1 was significantly decreased in poorly differentiated NSCLC than those in well and moderately differentiated cancers, and was inversely associated with the clinical stages of NSCLC patients." (PMID 26388699, 2015). "This study aims to incorporate ferulic acid into polymeric mixed micelles made of Pluronics and TPGS, in an attempt to enhance its solubility and stability, and to investigate its potential anti- cancer activity via miRNA-221/TP53INP1 axis-mediated autophagy on Caco-2 cancer cell line." (PMID 38267567, 2024). "Overexpression of TP53INP1 has been observed in PCa and is predictive of biological cancer relapse." (PMID 28163933, 2017). "However, it should be noted that there were many other targets of miR-155, such as FOXO3a, LKB1, TP53INP1, etc in cancers." (PMID 25965824, 2015).